TF (transferrin)
Diseases named in the same sentence as TF in open-access papers (continued):
Sharing a sentence is not in itself a finding about the gene and the disease.
tumor (continued). "Thus, decreasing cellular iron import by inhibiting transferrin and increasing cellular iron export by overexpressing ferroportin (Fpn) inhibit tumor growth." (PMID 36672419, 2023). "TF engages in cancer development, specifically tumor cell proliferation, survival, and metastasis." (PMID 37046617, 2023). "The cytotoxicity results showed that the conjugation of TF with PEGNIO could be a promising approach in targeted tumor treatment." (PMID 37953758, 2023). "TF regulates cytoskeletal remodeling and enhances tumor cell migration." (PMID 37046617, 2023). "Transferrin-conjugated liposomes showed increased tumor uptake." (PMID 37505047, 2023). "Besides stabilizing Myc RNA, Imp associates with many other mRNAs and has been shown to promote growth in another NB tumor, generated by the depletion of the prodifferentiation TF Pros." (PMID 37549261, 2023). "Interestingly, circulating TF-positive MPs or MP-TF activity in tumor tissue correlates with microvessel density." (PMID 37046617, 2023). "CS-SPIONs containing antitumor DOX and fluorescent dye Rhodamine B showed improved cell uptake and cell killing by inducing a concurrence of cell apoptosis and autophagy in the treated tumor U251 cells when conjugated with a tumor-specific ligand-transferrin (Tf)." (PMID 37765284, 2023). "Transferrin (Tf) has been widely used to functionalize NMs as it can be specifically recognized and taken up by Tf receptors overexpressed on the surface of various tumor cells." (PMID 36984157, 2023). "Given that 231 TFM tumor spheroids recruit more monocytes than 231 TF, we hypothesized that TAMs play a unique role in the release of monocyte chemoattractants." (PMID 38076998, 2023). "Intriguingly, treatment with TF NVs also significantly retarded tumor growth compared to the 293T NVs treatment, which may be due to the binding of serum iron ions to TF NVs which then induce ferroptosis." (PMID 37391845, 2023). "Additionally, this review will explore the latest studies on tumor targeting by functionalizing the surfaces of smart nanoparticles with tumor-specific ligands like antibodies, peptides, transferrin, and folic acid." (PMID 37919282, 2023). "SREBP2 could help circulating tumour cells to resist ferroptosis and acquire drug resistance by upregulating transcription of the iron carrier Transferrin (TF)." (PMID 37194000, 2023). "In addition, interestingly, some studies demonstrated that transferrin, a protein responsible for iron transporting, secreted by human and mouse neutrophils, promotes tumor metastasis." (PMID 35401569, 2022). "Interestingly, only the ferroptosis pathway was the most relevant Biological Process to the tumor and three genes were mapped to the ferroptosis pathway, which included transferrin (TF), ceruloplasmin (CP), and ferritin light chain (FTL)." (PMID 35340268, 2022). "Tumor cells expressing TF release TF-positive MPs, which are highly procoagulant." (PMID 35406450, 2022). "In this way, why a single TF perturbs so many different tumor-promoting features still stands." (PMID 35927248, 2022). "Established tumours thus had high cell and stromal expression of TF." (PMID 36046842, 2022). "Transferrin secreted by human neutrophils promotes tumor metastasis." (PMID 35401569, 2022). "However, it is important to note that improved uptake and cytotoxicity in vitro does not always translate to similar findings in vivo, as PEGylated MSNs showed higher tumor uptake compared to PEG-transferrin-modified MSNs in one study." (PMID 35214121, 2022). "Second, co-delivery of ART-type drugs with TF enhanced their tumor inhibition ability." (PMID 35214127, 2022). "The tumor center was characterized by a higher abundance of transferrin (TF), endoplasmic reticulum oxidoreductase 1 (ERO1)-like protein (ERO1A), EH domain-containing protein 1 (EHD1), keratin 5 (KRT5), serpin H1 protein (SERPINH1), and lactate dehydrogenase A (LDHA)." (PMID 35512017, 2022).
tumor (continued). "Moreover, the presence of TF on the liposome surface increased the concentration and retention time in the tumor, with the AUCtumor of TF-PEG liposomes 1.4 times higher than that of untargeted PEGylated liposomes." (PMID 36552793, 2022). "Tumor-infiltrating CD4+ T cells (C12_CD4) were associated with binding motif enrichment for cluster-specific TFs such as members of the POU domain family (POU2F1, POU2F2 and POU2F3), in addition to TF programs shared with dysfunctional CD8+ T cells." (PMID 35668194, 2022). "Several TAAs are overexpressed in HCC to meet the increased nutrient demand of tumor cells caused by their enhanced proliferation, such as receptors for asialoglycoproteins, transferrin, and folic acid, or correlate with the exacerbation of tumor features, such as MUC1, CEA, and TEM1." (PMID 36077433, 2022). "Moreover, TF is found to activate PAR-dependent tumor cell behavior, regulate integrin function and facilitate tumor angiogenesis." (PMID 35406450, 2022). "In addition, transferrin can also be used alone as a ligand to provide active tumor targeting capabilities of drug delivery systems." (PMID 35860027, 2022). "Similarly, GBM and cancer cells in general have increased levels of TFRs and transferrin conjugated nanoparticles increase tumor cell uptake by receptor mediated endocytosis." (PMID 35890360, 2022). "Liposome agents can specifically target tumors by binding to antibodies such as gender-affirming hormone (GAH), anti-EGFR, or anti-human epidermal growth factor receptor 2 (HER2) monoclonal antibodies, small molecules such as folic acid and transferrin, or tumor-targeting peptides such as RGD rings." (PMID 35248060, 2022). "In addition, several of the proteins related to the regulation of iron metabolism, including lactoferrin (LTF), transferrin receptors 1/2 (TFR1, TFR2), transferrin (TF), and ceruloplasmin (CP), have been identified as tumor markers." (PMID 35028002, 2022). "Moreover, the transferrin nanoparticles demonstrated the improved bioavailability of hypericin and better targeting at the tumour site." (PMID 34830287, 2021). "TF-MSCs had a similar effect on the migration of tumor cells as LC-MSCs." (PMID 33744858, 2021). "TF has good application prospects in the treatment of tumor diseases." (PMID 35082668, 2021). "Recently, we reported on the anti-tumor effects of RabMab1, our monoclonal antibody that binds the alternatively spliced isoform of human tissue factor (asTF), in a setting of orthotopic co-implantation with TF-expressing human PDAC cells." (PMID 34395257, 2021). "Also demonstrated in radio scintigraphy imaging of a tumor using γ-emitting gallium-67 citrate, when it was infused iv, it formed a complex with transferrin (90 kDa) in the plasma." (PMID 34071552, 2021). "Interestingly, we found divergent levels of stem-like genes in tumor cells induced by TF-MSCs in cell-cell direct and indirect contact culture system, which indicated additional mechanism resulted from cell-cell interaction." (PMID 33744858, 2021). "Additionally, TF-MSCs had much weaker effect on tumor invasion and metastasis compared with LC-MSCs although TF-MSCs and LC-MSCs exhibited similar ability to promote tumor growth." (PMID 33744858, 2021). "It relied upon transferrin for targeted drug delivery and could be activated by the tumour microenvironment." (PMID 34749740, 2021). "Transferrin expression by neutrophils was induced by tumor derived GM-CSF." (PMID 33679721, 2020). "Previous studies demonstrated that transferrin (Tf) is an essential component in cell growth and iron-requiring metabolic processes; thus, TfR1 is more highly expressed on rapidly growing cells such as on tumor cells." (PMID 32024821, 2020). "Examples of targeting moieties often exploited in nanomedicine are transferrin and folate, which target tumour cells overexpressing the corresponding receptors, or hyaluronic acid, which directs nanocarriers to CD44-overexpressing tumour cells, among many others." (PMID 32117671, 2020).
tumor (continued). "By conjugating transferrin-superparamagnetic nanoparticles with blood derived exosomes, enhanced tumor targeting could be observed under an external magnetic field, followed by significantly inhibiting tumor growth." (PMID 33628730, 2020). "Moreover, neutrophils can also secrete IL-16 and transferrin to accelerate metastasis and remain stemness of tumor cells." (PMID 33178575, 2020). "Given that increased vascularity of tumours could contribute to enhanced uptake of In-111-neutrophils, we also assessed the uptake of In-111-transferrin into tumours." (PMID 32887739, 2020). "Transferrin (39.5%) was the most abundant protein, followed by uncharacterized proteins (13.0%), vitelline membrane proteins (9.0%), peroxidase (5.7%), globulin (4.0%), keratin (3.9%), tumor markers (3.7%), actin (2.2%) and transferase (2.1%)." (PMID 32767984, 2020). "For instance, transferrin can be used as a targeting ligand for delivery into tumor cells through binding to the transferrin receptor, whose expression is enhanced in tumor cells to provide iron as a necessary cofactor for DNA synthesis and rapid cell proliferation." (PMID 32455572, 2020). "c-Myb is a known TF that could either activate or suppress the transcription of target genes, and is involved in tumor-related activities, such as proliferation, stemness, and metastasis." (PMID 33028809, 2020). "TfRs are highly overexpressed by GBM tumour cells and may be exploited as a target for systemic NP drug delivery, by raising antibodies against TfRs and the use of transferrin as a ligand-targeting moiety." (PMID 31728942, 2020). "We hypothesize that the entrapment of plumbagin within liposomes grafted with transferrin, whose receptors are overexpressed on many cancer cells, could result in a selective delivery to tumours after intravenous administration." (PMID 31341642, 2019). "It is proposed that Triapine acquires iron from transferrin in cells including tumor cells." (PMID 31234559, 2019). "Indeed, functionalization of NCs by transferrin (NC@Tf) or human serum albumin (NC@HSA) induces tumor cell killing when combined with PT, albeit less efficiently than NC@TRAIL." (PMID 31534529, 2019). "In order to increase the penetration of the GNPs through the BBB and their uptake by tumor cells, the GNPs were functionalized with different molecules on their surface (most commonly the RADyK group and the Transferrin) and/or the BBB itself was irradiated with paired-pulsed laser or MRgFUS." (PMID 29867737, 2018). "In addition, as the up-regulated differential RNA exhibiting the most TF activity, PLAU encodes a serine protease that acts as an activator in the ECM degradation in tumor development." (PMID 29351231, 2018). "The TF is a transcriptional activator, and functions as a tumor suppressor." (PMID 29764360, 2018). "FPN1+ iron-recycling monocytes may provide iron to tumor cells in their vicinity, especially in the liver, where these monocytes reside in large quantities, or after loading of ferric iron onto TF." (PMID 30534534, 2018). "In our previous study, we used transferrin (Tf) to deliver TC to tumour cells." (PMID 29348537, 2018). "Recent studies shows that Galectin-3 secreted by tumor cells binds TF-antigen on MUC1." (PMID 29507546, 2018). "The obtained Transferrin-ICG NAs showed effective active tumor-targeting, good biocompability, prominent dual-modal imaging as well as PTT efficacy, and could be adopted for theranostics of both subcutaneous and orthotopic brain tumors." (PMID 29755355, 2018). "In addition, α3β1 expressed in endothelial cells is proposed to play an important role in stabilizing TF-Ag/Gal-3 mediated tumor-endothelial adhesion." (PMID 30235349, 2018). "Furthermore, the lack of accumulation of non-functionalized NPs at the tumor site suggests that functionalization with transferrin is required for delivery of the NP across the BBB to the site of the tumor." (PMID 29777137, 2018).
tumor (continued). "ETS1 is a TF regulates genes involved in stem cell development, tumor genesis and metastasis." (PMID 29950928, 2018). "However, CNTs with transferrin on its surface have been found to contribute to oxidative damage, which leads to cell death or possible tumor formation/progression." (PMID 29439409, 2018). "Similarly, in B16F10 murine melanoma tumor models, the intravenous administration of tocotrienols entrapped in transferrin-bearing niosomes led to 50% complete disappearance of the tumors (Fu and Dufès, 2014)." (PMID 30534071, 2018). "The significantly improved tumor targeting efficiency of a transferrin-conjugated Lp system described in our previous work may be utilized for tumor neovasculature-targeted imaging and/or therapeutic gene delivery in vivo." (PMID 29499713, 2018). "Thus, if both types of cells were exposed to a transferrin solution beforehand, heating with radiofrequency waves would induce more dielectric heat in tumor cells than in normal cells." (PMID 30202000, 2018). "It has been demonstrated that activation of the coagulation cascade occurring in a cancer such as GC may arise from the direct capacity of tumor cells to express and release pro-coagulant factors, including TF, and to activate the host hemostatic system." (PMID 29518939, 2018). "TF expression in vivo was validated by immunostaining of TF in tumor sections." (PMID 28106852, 2017). "Whether there is a component of 68Ga-transferrin uptake in the tumor microenvironment due to infiltrating peripheral blood mononuclear cells is currently not understood." (PMID 28893116, 2017). "Recently, researchers have begun to focus on the effect of TF in the tumor microenvironment." (PMID 28106852, 2017). "To prove our hypothesis, we down-regulated TF expression in a lung tumor cell line and evaluated the procoagulant activity of tumor-derived TF in vitro." (PMID 28106852, 2017). "To determine whether TF-induced coagulation contributed to complement activation within the tumor microenvironment, we measured complement activation by immunohistochemical analysis." (PMID 28106852, 2017). "Receptor-mediated endocytosis of TF induced rapid tumor-cell-specific uptake of targeting nanoparticles, and the internalized nanoparticles could be effectively degraded to release functional drugs molecules in the cells." (PMID 29088799, 2017). "Consistent with previous studies in which TF’s procoagulant activity on A549 cells was blocked with an antibody, we used a short hairpin RNA (shRNA) to genetically interfere with the TF expression of A549 cells to validate the connection between TF and tumor cell procoagulant activity." (PMID 28106852, 2017). "Staining of C3b/iC3b/C3c revealed decreased C3b/iC3b/C3c deposition in tumor tissues derived from A549-shTF cells compared to tumor tissues derived from A549-vec cells, suggesting that TF-induced coagulation facilitated complement activation within the tumor microenvironment." (PMID 28106852, 2017). "Our findings reveal that TF expressed by cancer cells facilitates complement activation in the tumor microenvironment via triggering the coagulation cascade, which is an essential contributor to tumor progression by recruiting MDSC." (PMID 28106852, 2017). "The result suggested that TF-HA-CMC-PLGA NPs induced markedly disturbed tumor architecture." (PMID 29209206, 2017). "In our study, we found that TF-induced tumor progression could be blunted by C5aR antagonism, indicating that the influence of TF is complement dependent." (PMID 28106852, 2017). "The results from embryo development studies showed that teratomas from TF−/− embryonic stem (ES) cells exhibited equal tumor growth and frequency compared to normal ES cells, while another study suggested that blocking TF with an antibody in a xenotransplant tumor model resulted in delayed growth." (PMID 28106852, 2017).
tumor (continued). "The initiator of extrinsic coagulation, tissue factor (TF), and its non-coagulant isoform alternatively spliced TF (asTF) are closely associated with tumor development." (PMID 28106852, 2017). "In the current study, our data reveal that TF knockdown in A549 cells results in significantly decreased fibrin deposition in a xenotransplanted model, which reflected the coagulant state within the tumor microenvironment." (PMID 28106852, 2017). "If 68Ga-transferrin localization to the tumor were due to EPR, one could reasonably expect roughly equal accumulation of the radiotracer in all 14 hepatic lesions and values roughly equivalent to blood pool activity." (PMID 28893116, 2017). "C5aR antagonism blunted the effect of TF on tumor progression and decreased MDSC recruitment." (PMID 28106852, 2017). "Transferrin-coupling nanoparticles exhibit certain notable properties, including prolonged circulation time, low reticuloendothelial system uptake, and in vivo accumulation and internalization in tumor tissues." (PMID 28484093, 2017). "Some chemical anticarcinogenic drug (triapazamine, docorubicin, etc) and plant extract medicines (curcumin, paclitaxel, etc), conjugated directly or via nanoparticles to transferrin, were designed for tumor-targeting delivery to increase the efficacy of therapy, meanwhile decreased side effects." (PMID 28484093, 2017). "This dramatic upregulation of TF isoforms may be attributed to the existence of common stimuli from the tumor microenvironment, such as inflammation and hypoxia." (PMID 28106852, 2017). "When encountering tumor tissue, they could also extravasate via the leaky vessels by the EPR effect and achieve active tumor targeting through specific interaction between TF and TFR." (PMID 27377918, 2016). "Interestingly, TF-8arm- PEG-DHA NPs treatment exhibited greater tumor volume inhibition and survival benefit than 8arm-PEG-DHA NPs owing to the target ligand TF." (PMID 27377918, 2016). "The higher uptake of 177Lu‐C1P5 noted in the tumor and slower clearance from the blood and blood‐rich organs, such as the liver, can be explained by the fact that 177Lu, a trivalent metal, preferentially binds to blood proteins such as transferrin." (PMID 26625938, 2016). "In particular, TF-8arm-PEG-DHA NPs showed the highest anti-tumor efficiency at all concentrations." (PMID 27377918, 2016). "In tumour tissues, the pH can drop to 6–7, in lysosomes to 4–5 and in endosomes the pH drops to 5.5 and plays a key role in, for example, the release of Fe3+ from its transport protein transferrin." (PMID 25666066, 2015). "However, it is likely that increased levels of a TF in a tumor can result in higher binding at a partially methylated enhancer, directly leading to loss of DNA methylation." (PMID 25994056, 2015). "In all, we identified 38 enhancer-TF pairs in the 10 tumor types." (PMID 25994056, 2015). "Ruthenium(III) from these complexes may be delivered to tumour cells by the FeIII transport protein serum transferrin, receptors for which are over-expressed on cancer cells." (PMID 25666066, 2015). "As the tumour may be responsible for increased iron concentrations in the plasma, the transport may also be corrupted at the transferrin/transferrin receptor level." (PMID 25435931, 2015). "The distribution of RGD-LP, TF-LP and RGD/TF-LP was markedly higher in the whole spheroid, indicating that RGD and TF may effectively increase the tumor uptake and penetration." (PMID 25289086, 2014). "However, proliferation and survival of some tumour cell lines are correlated with transferrin uptake." (PMID 25162584, 2014). "Subsequently, TF improves the cellular uptake of LP by TFR-expressing tumor cells." (PMID 25289086, 2014). "The overexpression of annexin A10 protein, BCL-2-like protein, calgizzarin, HSP beta-6, RhoGAP-activating protein 7, transferrin, and vimentin among others referred to healthy samples may indicate the presence of tumor in bones." (PMID 24475253, 2014).